RN7SKP108 (RN7SK pseudogene 108)
Gene: Miscellaneous RNA gene on chromosome 14 (96,638,187 to 96,638,514, reverse strand). Ensembl gene ENSG00000223299.
Homologues: Orthologues: chimpanzee 7SK (99% identical), mouse Gm56101 (57% identical). Paralogues in human: RN7SKP79 (67% identical), 7SK (66% identical), RN7SKP240 (65% identical), RN7SKP78 (65% identical), RN7SKP124 (65% identical), RN7SKP180 (64% identical), RN7SKP217 (64% identical), RN7SKP214 (64% identical), RN7SKP176 (64% identical), RN7SKP36 (64% identical), RN7SKP160 (63% identical), RN7SKP47 (63% identical), and 285 more.